RPL18 (ribosomal protein L18)
Description:
Component of the large ribosomal subunit. The ribosome is a large ribonucleoprotein complex responsible for the synthesis of proteins in the cell.
Synonyms: L18; eL18; DBA18
Tractability: Small molecule: an approved drug acts on it; a structure with a bound ligand is known; a high-quality ligand is known. PROTAC: UniProt records ubiquitination sites on it; ubiquitination databases record sites on it; its protein half-life has been measured; a small molecule that binds it is known. Other modalities: a drug acting on it is in phase 2 or 3 trials.
Target class: Other cytosolic protein
Gene: Protein-coding gene on chromosome 19 (48,615,284 to 48,619,213, reverse strand). Ensembl gene ENSG00000063177.
Subcellular location: Cytoplasm, cytosol; Cytoplasm; Rough endoplasmic reticulum
Subcellular location (Human Protein Atlas): Cytosol; Endoplasmic reticulum; Nucleoli
Pathways (Reactome):
Metabolism of proteins: Eukaryotic Translation Termination; Formation of a pool of free 40S subunits; GTP hydrolysis and joining of the 60S ribosomal subunit; L13a-mediated translational silencing of Ceruloplasmin expression; PELO:HBS1L and ABCE1 dissociate a ribosome on a non-stop mRNA; Peptide chain elongation; Ribosome Quality Control (RQC) complex extracts and degrades nascent peptide; SRP-dependent cotranslational protein targeting to membrane; ZNF598 and the Ribosome-associated Quality Trigger (RQT) complex dissociate a ribosome stalled on a no-go mRNA
Metabolism of RNA: Major pathway of rRNA processing in the nucleolus and cytosol; Nonsense Mediated Decay (NMD) enhanced by the Exon Junction Complex (EJC); Nonsense Mediated Decay (NMD) independent of the Exon Junction Complex (EJC)
Disease: Dengue Virus-Host Interactions; Viral mRNA Translation
Cellular responses to stimuli: Response of EIF2AK4 (GCN2) to amino acid deficiency
Developmental Biology: Regulation of expression of SLITs and ROBOs
Metabolism: Selenocysteine synthesis
Gene Ontology:
Molecular function: protein binding; structural constituent of ribosome; RNA binding
Biological process: cytoplasmic translation; negative regulation of myoblast fusion; spermatogenesis; striated muscle contraction; translation
Cellular component: cytosol; cytosolic large ribosomal subunit; cytosolic ribosome; endoplasmic reticulum; focal adhesion; membrane; nucleus; cytoplasm; rough endoplasmic reticulum; ribosome
Genetic constraint (gnomAD): Loss-of-function variants: 4 observed, 25.07 expected, observed/expected ratio (o/e) 0.16, 90% interval 0.078 to 0.37. The upper end of that interval is the gene's LOEUF score, 0.37, which puts it in group 1 of 6, group 1 being the genes least tolerant of losing a copy. Missense variants: 179 observed, 279.11 expected, observed/expected ratio (o/e) 0.64, 90% interval 0.57 to 0.73. Synonymous variants: 129 observed, 106.76 expected, observed/expected ratio (o/e) 1.21, 90% interval 1.05 to 1.4.
Homologues: Orthologues: chimpanzee RPL18 (100% identical), macaque RPL18 (100% identical), rabbit RPL18 (93% identical), zebrafish rpl18 (83% identical), pig RPL18 (73% identical), Drosophila melanogaster RpL18 (69% identical), tropical clawed frog rpl18 (69% identical), Caenorhabditis elegans rpl-18 (66% identical).
Diseases named in the same sentence as RPL18 in open-access papers:
RPL18 is named in the same sentence as 18 diseases in open-access papers, as found by Europe PMC text mining. Sharing a sentence is not in itself a finding about the gene and the disease. The quoted sentences say what the papers report.
viral infection (5 papers, 2019 to 2024). "The association of ribosomal proteins such as RPL6, RPL18 and RPL24 along with other RPs has been reported as an essential step in translational transactivation in plants and animals upon viral infection." (PMID 36616305, 2023). "DEGs unique to infected cells mapped to host defense (MYD88, C3, CASP4, JAK2, and OSM), viral infection (RNASE6 and SVVORFs), and protein synthesis (RPL18 and RPS16)." (PMID 38887303, 2024). "RPL18 and RPL7 have been also found in siRNA screens performed with yellow fever and West Nile virus." (PMID 31040842, 2019). "Different RPs like RPL10, RPL13, RPL18, RPL24, and RPS6 are involved in viral infections of plants." (PMID 33995313, 2021).
breast carcinoma (2 papers, 2012 to 2017). "On the other hand, some down-regulated ribosomal proteins, such as RPL35A, RPL18 and RPL14 that we find in both the breast cancer tissue and cell lines have received relatively little attention and might be worth pursuing." (PMID 22346740, 2012).
colon cancer (2 papers, 2021 to 2023). "Further analysis revealed that some of these genes, notably rps15, rpl11, rpl18, and rpl36, are significantly increased in primary adenocarcinoma tissue samples and co-ordinately predict for worse overall survival of colon cancer patients." (PMID 37888706, 2023). "On the other hand, RPL11 and RPL18 proteins had moderate intensity in colon tissue, whereas RPS15 and RPL36 showed strong staining intensity in colon cancer tissue." (PMID 37888706, 2023). "We found that higher expression of RPS15, RPL11, RPL18 and RPL36 could individually predict worse overall survival (OS) of patients with colon cancer compared to the low expression of these genes." (PMID 37888706, 2023). "Finally, based on this evidence, we hypothesized that since these genes are implicated in similar pathways related to ribosomal biosynthesis and protein translation, RPS15, RPL11, RPL18 and RPL36 expression levels may coordinately predict the survival of patients with colon cancer." (PMID 37888706, 2023).
dengue virus infection (2 papers, 2022 to 2023). "It has been previously observed that during dengue virus infection, RPL18 is redistributed to the perinuclear region and RPL18 inactivation results in reduced viral translation and replication." (PMID 35815389, 2022). "Notably, studies have reported that in dengue virus infection, the silencing or the knockdown of ribosomal proteins RPL18 and RPLP1/2 significantly reduced the viral replication and translation as well as the viral yield, indicating the importance of ribosomal proteins in the virus life cycle." (PMID 37022180, 2023).
anemia (1 paper, 2020). A reduction in the number of red blood cells, the amount of hemoglobin, and/or the volume of packed red blood cells. "Detailed analyses showed that mutation in rpl18 leads to anemia and severe morphological abnormalities in zebrafish." (PMID 32075953, 2020). "Overall, these findings demonstrated that erythropoiesis was specifically affected in rpl18 mutants and the anemia was due to a late-stage terminal maturation of erythroid cells." (PMID 32075953, 2020). "Furthermore, we found inhibitors of JAK2 or STAT3 phosphorylation could rescue anemia in rpl18 mutants." (PMID 32075953, 2020).
colorectal cancer (1 paper, 2023). A primary or metastatic malignant neoplasm that affects the colon or rectum. "Recently, it has been reported that a mutation in the RPL18 protein acts as a neo-epitope, eliciting a strong reaction from endogenous CD8 T cell responses in colorectal cancer mouse models; this could identify the mutant form of RPL18 as a potential target of immunotherapeutic strategies in CRC." (PMID 37888706, 2023).
cyst (1 paper, 2023). A sac-like closed membranous structure that may be empty or contain fluid or amorphous material. "When RpL6 or RpL18 was knocked down in early germ cells driven by nanos-gal4, tiny testes were formed, germ cells were lost, and cyst cells accumulated." (PMID 36831240, 2023). "In contrast, knocking down RpL6 or RpL18 in cyst cells resulted in an increase in the number of undifferentiated germ cells and subsequent tumor development." (PMID 36831240, 2023).
Ebola (1 paper, 2020). "For example, 60S ribosomal protein L18 (RPL18) is found to be incorporated into Ebola virions, and the reduced expression of RPL18 effectively represses Ebola virus infection." (PMID 32420802, 2020).
influenza (1 paper, 2025). An acute viral infection of the respiratory tract, occurring in isolated cases, in epidemics, or in pandemics; it is caused by serologically different strains of viruses (influenzaviruses) designated A, B, and C, has a 3-day incubation period, and usually lasts for 3 to 10 days. "For influenza, discriminatory ribosomal genes included RPL7A, RPL13, RPL18, RPL23A, RPLP2, RPS2, and RPS4X." (PMID 41020849, 2025).
sarcoidosis (1 paper, 2025). Sarcoidosis is a multisystemic disorder of unknown cause characterized by the formation of immune granulomas in involved organs. "In addition, membrane-associated HGFA, ILF3, RAB7A, and RPL18 in alveolar macrophages were proposed as diagnostic biomarker candidates for sarcoidosis 58,59." (PMID 41279897, 2025).
tumor (12 papers, 2021 to 2024). "Only forced expression of these neoantigens but not OvaI257-264 in MC38-K cells via electroporation of matching neoantigen encoding RNAs resulted in significant recognition of the tumor cells by Adpgk- or Rpl18-TCR transduced T cells." (PMID 36969213, 2023). "The impairment of CD8 T cell response did not depend on the source of antigen, as it was observed with antigens of viral (HPV-E7 and VSV-GP) origin as well as tumor specific neoantigens (adpgk, reps-1, rpl-18), which exhibit a wide range of immunogenicity." (PMID 38893156, 2024). "After co-culture with IFNγ pre-stimulated MC38-L cells, Rpl18-TCR transduced T cells also showed tumor recognition." (PMID 36969213, 2023). "Despite no clear trend for dominance of one antigen-specificity, the frequency of Rpl18-specific CD8+ T cells was higher in MC-38 tumor-bearing compared to tumor-free animals." (PMID 34885215, 2021). "The functional TCR avidity of the different antigen specificities (Adpgk, Reps1, Rpl18) was assessed in splenocytes from MC-38 tumor-bearing mice." (PMID 34885215, 2021). "This indicated a strong impact of the MC-38 tumor as a source of Rpl18 antigen, which was further boosted by heterologous vaccination." (PMID 34885215, 2021). "With regards to tumor-dLNs, KV vaccination significantly increased Adpgk-, Reps1- and Rpl18-specific CD8+ T cells compared to controls." (PMID 34885215, 2021). "In contrast to KPC3 tumors, αTGF-β administration significantly increased the Reo-induced influx of total T cells in MC38 tumors, as well as the frequency of reovirus-specific (μ1133–140 Tm+) and tumor-specific (Rpl18 Tm+) CD8+ T cells compared with the group that received Reo only." (PMID 36860656, 2023). "The (PDT + CTLA-4)-gel multi laser treatment also induced more tumor neo-antigen (ADPGK and RPL18)-specific CD8+ T cells than the control group." (PMID 35974207, 2022). "Similar to as in the blood, the frequency and number of tumor-infiltrating antigen-specific CD8+ T cells were further increased when the sum of Adpgk-, Reps1- and Rpl18-specific CD8+ T cells was considered." (PMID 34885215, 2021). "The presence of tumor-specific T cells among splenocytes, obtained from these mice, was investigated by stimulation, with D1 dendritic cells preloaded with the MC38 neoepitopes Adpgk or Rpl18, and subsequent analysis of intracellular cytokine production." (PMID 34575546, 2021). "Furthermore, the ability of the treatment to induce tumor-specific immune responses was investigated by stimulating the splenocytes of treated, tumor-bearing mice ex vivo with the MC38 neoepitopes Adpgk and Rpl18." (PMID 34575546, 2021). "In addition, polyfunctional Adpgk but not Reps1 nor Rpl18-specific tumor-infiltrating CD8+ T cells were observed in the KV group." (PMID 34885215, 2021). "In support of this hypothesis, we did not observe this competition in non-tumor-bearing animals, where Rpl18-specific CD8+ T-cell frequencies were decreased compared to tumor-bearing animals arguing that the tumor influences this competition phenomenon." (PMID 34885215, 2021). "Importantly, the combination of CD3xTRP1 with tumor-nonspecific OVA, as well as the tumor-specific neoantigen Rpl18 SLP22 vaccines adjuvanted with CpG, both resulted in complete antitumor responses in almost all mice." (PMID 38167722, 2024).
cancer (4 papers, 2017 to 2022). A tumor composed of atypical neoplastic, often pleomorphic cells that invade other tissues. "This ability of PDT to function as an in situ vaccination modality has often been hypothesized; however, it has, to our knowledge, only been shown for exogenous antigens (ovalbumin) and not for cancer neoepitopes (Rpl18 and Adpgk)." (PMID 34575546, 2021).
infection (2 papers, 2020 to 2022). The state of being infected such as from the introduction of a foreign agent such as serum, vaccine, antigenic substance or organism. "The stability ranking at different developmental stages associated with infection of PWN was as the following: TER > RPL7 > RPS5 > Zdhhc15 > EF1-γ > RPL18 > Tmub1 > SNX6 > ATPase > TFAM > α-TUB > EIF > TPI > COX7." (PMID 35547586, 2022). "For different developmental stages associated with infection of PWN and pupae treated with PWN, two conditions had similar results that RPS5, RPL18, and RPL7 were identified as the most stable genes, but α-TUB, COX7, EIF, and SNX6 were poor stable genes." (PMID 35547586, 2022).
RPL18 also shares sentences with these, for which no sentence is quoted: Cerebral ischemia (2 papers); adenocarcinoma (1); co-infection (1); colon adenocarcinoma (1); Stroke (1).